NLRP1 (NLR family pyrin domain containing 1)
Diseases named in the same sentence as NLRP1 in open-access papers (continued):
Sharing a sentence is not in itself a finding about the gene and the disease.
vitiligo (continued). "Aside from familial mutations in NLRP1 that predispose humans to skin cancer, common polymorphisms at the NLRP1 locus are associated with resistance to glucocorticoid treatment in pediatric IBD, and several autoimmune diseases such as vitiligo, celiac disease and psoriasis." (PMID 30214011, 2018). "Recent studies reveal that NLRP1 gene variants confer susceptibility to non-infectious skin-associated autoinflammatory and autoimmune diseases, including vitiligo, lupus erythematosus, and psoriasis." (PMID 28422993, 2017). "Our data did not provide evidence of an association between the NLRP1 rs12150220, rs2670660, and rs6502867 genotypes and the risks of vitiligo in the overall population." (PMID 29152150, 2017). "Overall, rs2670660 and rs6502867 NLRP1 polymorphisms seem not to be associated with the risk of vitiligo-associated autoimmune diseases." (PMID 29152150, 2017). "Since skin hypopigmentation in VKH disease resembles generalized vitiligo, NLRP1 might be involved in the pathogenesis of VKH." (PMID 25097674, 2014). "It is interesting to note that some of the NLRP1-intergenic SNPs for vitiligo and other diseases [including systemic lupus erythematosus (SLE);] also showed suggestive associations for HDL in LLFS (e.g., rs995298: p = 7.09E-06, rs8065677: p = 2.98E-04, rs2716900: p = 4.28E-04)." (PMID 24917880, 2014). "In addition, NLRP1 and IL-1β levels in the skin may represent better markers than detection of lymphocyte infiltration to monitor vitiligo activity." (PMID 32528469, 2020). "However, we did not observe a strong association between NLRP1 rs12150220, rs2670660, or rs6502867 and vitiligo risk, according to the currently very limited data." (PMID 29152150, 2017). "Thus, NLRP1 rs2670660/rs12150220 haplotypes are unlikely to be related to vitiligo-associated autoimmune diseases risks." (PMID 29152150, 2017). "Interestingly, our recent study shows significant association of NLRP1 promoter variants with GV and NLRP1 overexpression in patients compared to controls; which might lead to increased IL1B production in vitiligo patients." (PMID 25221996, 2014). "Some NLRs, such as NLRP1 and NLRP3, are activated in response to oxidative stress or cellular damage in vitiligo; NLRP1 and NLRP3 are components of the inflammasome complex that, once activated, releases caspase 1 and IL-1β and IL-18." (PMID 34768860, 2021). "Both nucleotide-binding oligomerization domain, leucine rich repeat and pyrin domain containing 1 (NLRP1) and the NLRP3 inflammasome have been reported to act in the pathogenesis of vitiligo." (PMID 34768860, 2021). "Remarkably, the expression of NLRP1 and IL-1β was almost absent in lesional skin of vitiligo patients, similar to that in the skin of healthy control subjects." (PMID 37325658, 2023). "Concerning the involvement of inflammasome in skin homeostasis, it has been shown that both NLRP1 and NLRP3 are present within the cutaneous tissue and participate in various skin pathologies, such systemic lupus erythematosus, vitiligo, psoriasis, and atopic dermatitis." (PMID 35428946, 2022). "In another study, the expression levels of NLRP1 and IL-1β in perilesional vitiligo/non-segmental vitiligo skin were found to be significantly associated with disease progression." (PMID 29915579, 2018). "Moreover, NLRP1 was reported to contribute to SLE in families suffering SLE and vitiligo or other autoimmune or autoinflammatory diseases and it has been recently found to be associated with SLE in a Brazilian population." (PMID 22531499, 2012).
melanoma (39 papers, 2012 to 2025). A malignant, usually aggressive tumor composed of atypical, neoplastic melanocytes. "In a case–control study conducted in Sweden, findings revealed a notable prevalence of the NLRP1 variant (rs12150220) among female melanoma patients with fair skin, demonstrating robust correlations with nodular melanoma." (PMID 40237399, 2025). "Polymorphisms in the inflammasome sensor NLRP1 have been linked to cancer susceptibility, including mesothelioma, melanoma, and epidermal hyperplasia." (PMID 40237399, 2025). "NLRP3 and NLRP1 inflammasomes polymorphisms were associated with susceptibility to melanoma in a Swedish case-control study." (PMID 37020871, 2023). "Changes in abundance at the protein and phosphorylation site levels revealed patient-specific over-represented pathways, notably linked to melanoma development (MAPK1 activation) or immunotherapy (NLRP1 inflammasome)." (PMID 34771574, 2021). "The polymorphism or mutation of the NLRP1 gene was found to be tightly associated with the progression of melanoma." (PMID 31492049, 2019). "SNPs of NLRP3 and particularly of NLRP1 are associated with the development of melanoma." (PMID 36293159, 2022). "In the second grade, IL-1R is expressed and in the third progressive stage the NLRP3 inflammasome is active constitutively, a correlation has been shown between the NLRP1 and NLRP3 variations and melanoma risk, with the greatest correlation between NLRP1 and nodular melanoma." (PMID 30447690, 2018). "Many studies with a focus on genetic risk factors in human NLRP1 describe SNP rs11651270, causing the missense mutation M1184V, to have dichotomous effects on the development of a multitude of autoimmune syndromes like asthma, inflammatory bowel disease, malignant melanoma, or diabetes." (PMID 36309085, 2022). "explored the connection between the inflammasome sensor NLRP1 and acquired drug resistance to temozolomide in melanoma, as NACHT, LRR, and PYD domains‐containing protein inflammasomes play a role in IL‐1β maturation and NF‐κB activation." (PMID 40237399, 2025). "Their findings indicated heightened expression of NLRP1 in melanoma cells that had become resistant to temozolomide." (PMID 40237399, 2025). "The contribution of IL18+ cells and NLRP1+ cells was decreased in stromal areas in melanoma compared with control samples by IHC experiment (melanoma and control groups, n = 4, respectively)." (PMID 37620327, 2023). "NRLP1 has been implicated in melanoma, with one study examining 216 melanoma tissue samples and 13 human melanoma cell lines to report that NLRP1 expression was elevated in melanoma." (PMID 37497237, 2023). "In combination, the findings suggested that GZMA, GSDMB, NLRP1, CHMP4A, and IL18 deficiency, at least in part, are responsible for melanoma." (PMID 37620327, 2023). "A previous study reported that NLRP1 promotes melanoma growth by enhancing inflammasome activation and suppressing apoptotic pathways." (PMID 35246158, 2022). "NLRP1 is demonstrated to promote melanoma development via improving inflammasome activation, and overexpression of NLRP1 in breast cancer cells promotes proliferation, tumorigenesis in nude mice." (PMID 35574984, 2022). "In this paper, we provide evidence that depicts NLRP1 as a potential therapeutic target in drug-resistant melanoma to TMZ." (PMID 32899791, 2020). "Recently, we demonstrated the involvement of NLRP1 in the acquired resistance of metastatic melanoma cells to the chemotherapy temozolomide (TMZ) by amplifying IL-1β signaling and activating nuclear factor κB (NF-κB) activity." (PMID 33396632, 2020). "This is the first report to link the MAPK/ERK signaling to NLRP1 in melanoma through the ATF4 regulation." (PMID 33396632, 2020). "In the current work, we verified that the regulation of the NLRP1 gene promoter activity in MAPK inhibitor-resistant melanoma cells is via PKA." (PMID 33396632, 2020).
melanoma (continued). "These two different drug treatments activate distinct signaling pathways that converge on the ATF4/NLRP1 axis to regulate melanoma growth." (PMID 33396632, 2020). "The aim of this study was to further determine the role of NLRP1 in acquired drug resistance in melanoma." (PMID 32899791, 2020). "Among a dozen NLRP proteins, NLRP1 promotes melanoma by increasing IL-1β secretion and suppresses apoptosis by inhibiting CARD-containing caspase activity." (PMID 33396632, 2020). "Because NACHT, LRR and PYD domains-containing protein (NLRP) inflammasomes mediate IL-1β maturation and NF-κB activation, we investigated the role of inflammasome sensor NLRP1 in acquired drug resistance to temozolomide (TMZ) in melanoma." (PMID 32899791, 2020). "Additional findings of this study lead to the conclusion that NLRP1 possessed tumor-enhancing role in melanoma cells." (PMID 33015196, 2020). "In the presence of TG, both ATF4 and NLRP1 were upregulated at mRNA levels (respectively), suggesting that NLRP1 expression responds to ER stress activation in melanoma cells." (PMID 33396632, 2020). "It has been shown that NLRP1 exhibited a dual role as it promoted melanoma growth by activating inflammasome and suppressing apoptosis." (PMID 32340261, 2020). "We, for the first time, demonstrate that NLRP1 inflammasome is involved in the development of acquired drug resistance of melanoma." (PMID 32899791, 2020). "The inflammasome sensor, NACHT, LRR, and PYD domains-containing protein 1 (NLRP1), is responsible for IL-1β maturation and itself is a melanoma tumor promoter." (PMID 33396632, 2020). "NLRP1 facilitated melanoma growth via depressing the apoptotic pathway by inhibiting the activities of caspase-2, -3, -7 and -9." (PMID 31492049, 2019). "The anti-inflammatory activity of CP by suppressing the NLRP1-related inflammatory pathway contributes to the suppression of melanoma progression." (PMID 30149677, 2018). "Another study evaluated the association of the genetic polymorphisms of NLRP3 (Q705K and rs10733113), CARD-8 (rs2043211), and NLRP1 (rs6502867 and rs12150220) in Swedish patients with sporadic malignant melanoma (MM)." (PMID 30447690, 2018). "elucidate that the NLRP1 inflammasome plays a dual role in melanoma progression by promoting inflammasome activation, which in turn augments the pyroptotic cell death pathway while simultaneously impeding apoptotic mechanisms, thus contributing to tumor growth." (PMID 40237399, 2025). "These phenomena indicated that NLRP1 inflammasomes promote melanoma growth." (PMID 37020871, 2023). "Zhai mentioned in his paper that NLRP1 expression was upregulated in melanoma cells." (PMID 37020871, 2023). "Moreover, in Nlrp1-/- metastatic melanoma cells, decreased inflammatory cytokines secretion and NF-κB activity were observed, while increased caspase-2/-9 activity and promoted apoptosis." (PMID 37020871, 2023). "Therefore, there is evidence to suggest that NLRP1 promotes melanoma growth by enhancing inflammasome activation and inhibiting apoptosis in melanoma cells." (PMID 37497237, 2023). "The initial findings from the enzyme-linked immunosorbent assay (ELISA) indicated a statistically significant downregulation of pyroptosis protein expression in melanoma patients when compared to the control group, especially NLRP1, GZMA, and GSDMB, followed by CHMP4A and IL18." (PMID 37620327, 2023). "Some academics suggested that NLRP1 could promote melanoma proliferation through inflammatory activation enhancing, which was associated with apoptosis." (PMID 36276158, 2022). "Similarly, the NLRP1 inflammasome promotes melanoma growth by increasing Caspase-1 activity and promoting IL-1 β secretion." (PMID 35246158, 2022). "However, another study showed that the increase in NLRP1 expression and functional activity can promote the growth of melanoma." (PMID 36186792, 2022).
melanoma (continued). "Furthermore, TMZ-resistant melanoma cells showed increased expression of NLRP1 and activation of the NLRP1 inflammasome, leading to the maturation and secretion of IL-1β." (PMID 34299198, 2021). "The NLRP1 inflammasome could serve an instigator of chronic myeloid leukemia, melanoma, osteosarcoma, breast cancer, and prostate cancer." (PMID 33658393, 2021). "Therefore, we first determined the mechanism of NLRP1 regulation by the MAPK/ERK pathway using drug-sensitive melanoma cells." (PMID 33396632, 2020). "A melanoma-specific role of other inflammasome-related protein NLRP1 has also been envisaged." (PMID 32340261, 2020). "Therefore, it will be interesting to evaluate the regulatory role of ATF2 in NLRP1-mediated targeted therapy resistance in melanoma." (PMID 33396632, 2020). "However, further study revealed an additional function of NLRP1 assessed exclusively in metastatic melanoma cells." (PMID 32340261, 2020). "ATF4-mediated NLRP1 expression and IL-1β efflux may be the mechanistic basis for melanoma tumorigenesis and drug resistance via shaping the inflammatory tumor microenvironment." (PMID 33396632, 2020). "Overall, this work added a new understanding of NLRP1 in melanoma biology." (PMID 33396632, 2020). "Interestingly, ATF4/NLRP1 regulation by the MAPK/ERK pathway uses distinct mechanisms in melanoma cells before and after the acquired resistance to targeted therapy." (PMID 33396632, 2020). "Given the role of these signaling pathways in melanoma tumorigenesis and progression, downstream NLRP1 may be an important executor." (PMID 33396632, 2020). "Indeed, we demonstrated that NLRP1 plays a role in vemurafenib resistance in melanoma through transcriptional regulation by ATF4, in which activation is mediated by the MAPK/ extracellular signal-regulated kinase pathway." (PMID 32899791, 2020). "Because drug-tolerant cancer cells become cross-tolerant to other classes of cancer drugs, NLRP1 might be a suitable therapeutic target in drug-resistant melanoma, as well as in other cancers." (PMID 32899791, 2020). "Since the inflammatory microenvironment provides melanoma tolerance to targeted therapy, targeting NLRP1/IL-1β may be an important strategy to improve MAPK inhibitor efficacy." (PMID 33396632, 2020). "A recent report has pointed out that NLRP-1 is expressed constantly in human melanoma." (PMID 30149677, 2018). "NLRP1 (NLR family pyrin domain containing 1), confirmed as a proinflammatory protein in melanoma progression, was downregulated significantly by CP, as were the NLRP1-related caspase activation and recruitment domains (CARD) proteins, including caspase-1 and caspase-4." (PMID 30149677, 2018). "However, some studies suggest that SARS-CoV-2 infection is associated with other inflammasomes as well; such as NLRP1, absent in melanoma-2 (AIM-2), caspase-4 and -8 which were mostly found during dsRNA virus or bacteria infection." (PMID 37360532, 2023). "Our findings support that NLRP1 may be a promising molecular target for melanoma treatment." (PMID 33396632, 2020). "The functions of NLRP1 as both a melanoma tumor promotor and an apoptosis suppressor lead us to hypothesize that NLRP1 plays a role in the development of acquired drug resistance in human melanoma." (PMID 32899791, 2020). "In addition, NLRP1 was mainly confined in the cytosol of melanoma cells, suggesting that cellular localization of NLRP1 might also promote its interaction with caspases." (PMID 32340261, 2020). "However, despite upregulated MGMT expression, the resistant mechanism was independent of MGMT, and the cells that acquired TMZ resistance showed increased NLRP1 inflammasome activation, NF-κB activity, and IL-1β secretion, which contributed to the melanoma cells’ resistance to TMZ." (PMID 32899791, 2020). "Targeting NLRP1 may improve the therapeutic efficacy of targeted therapy in melanoma." (PMID 33396632, 2020).
melanoma (continued). "Therefore, we hypothesized that NLRP1 contributes positively to the development of drug resistance in human melanoma." (PMID 33396632, 2020). "Downregulation of other genes associated with this pathway, such as the Nod1 gene that promotes inflammation and Nlrp1 gene that functions to induce apoptosis, would also be expected to contribute to immune escape, enhanced survival, and the overall protumorigenic nature of this melanoma." (PMID 26441959, 2015). "One such effector is the inflammasome sensor NLRP1 (NACHT, LRR, and PYD domains-containing protein 1), which promotes melanoma growth by facilitating IL-1β maturation." (PMID 40872623, 2025). "Histologically, melanoma tissues had fewer positive cells percentage of pyroptosis-related genes (PRGs), GZMA, GSDMB, NLRP1, IL18, and CHMP4A in epidermal than in normal skin." (PMID 37620327, 2023). "Histologically, melanoma tissues had fewer positive cells percentage of PRGs, GZMA, GSDMB, NLRP1, IL18, and CHMP4A in epidermal than in normal skin." (PMID 37620327, 2023). "Among the 14 NLRP protein family members, NLRP3 is the most studied, while NLRP1 is unique because of its caspase recruitment domain (CARD) domain, which allows NLRP1 to directly bind CARD-containing caspases and inhibit melanoma cell apoptosis." (PMID 32899791, 2020). "We provide further evidence that NLRP1 lies downstream of the ER stress signaling cascade, possibly through the PERK/ATF4 in melanoma cells." (PMID 33396632, 2020). "Lastly, we determined the role of NLRP1 in cell growth and colony formation of MAPK inhibitor-resistant melanoma cells." (PMID 33396632, 2020). "In summary, we demonstrated that NLRP1 functions downstream of the MAPK/ERK signaling via ATF4 and is a player of targeted therapy resistance in melanoma." (PMID 33396632, 2020). "In the present study, we further demonstrate, for the first time, that NLRP1 functions downstream of the MAPK/ERK signaling and contributes to acquired targeted therapy resistance in melanoma." (PMID 33396632, 2020). "Later, it was demonstrated that NLRP1 rather than NLRP3 promotes melanoma growth and suppresses apoptosis." (PMID 36293159, 2022). "NLRP1 and NLRP3 are two key NLRP family members for IL-1β secretion in melanoma." (PMID 33396632, 2020). "In parental melanoma cells, the RSK2/ATF4 axis acts as the hub between the MAPK/ERK signaling and NLRP1; however, MAPK inhibitor-resistant cells seem to lose this signaling hub and switch to the cAMP/PKA pathway to redirect NLRP1 expression." (PMID 33396632, 2020). "NLRP1 is expressed at low levels in melanoma and nonmelanoma skin cancers, possibly due to its DNA hypermethylation." (PMID 33396632, 2020). "NLRP1 is considered to be a tumor suppressor, but aberrant NLRP1 inflammasome activation due to gain-of-function mutations has been associated with cancers and autoimmune diseases, which could reasonably explain why some melanoma cell lines, if not all, are capable of secreting IL-1β." (PMID 33396632, 2020). "To understand the relationship between the MAPK/ERK pathway and NLRP1, we tested whether ATF4 works upstream of NLRP1 expression in metastatic melanoma cells." (PMID 33396632, 2020). "Although the clinical evidence implied that melanoma skin tissue reduced GZMA, GSDMB, NLRP1, IL18, and CHMP4A expression in epidermal, however, the result obtained with bulk-sorted samples could not explain the main scientific questions on cell sources heterogeneity." (PMID 37620327, 2023). "These two distinct properties of NLRP1 have been shown to play integral roles in the promotion of tumor growth and survival in human melanoma, and, therefore, it was not surprising to discover that NLRP1 is involved in acquired drug resistance to TMZ in melanoma." (PMID 32899791, 2020). "Consequently, NLRP1 inflammasomes have been shown to promote tumorigenesis in late-stage melanoma and non-melanoma skin cancers." (PMID 32899791, 2020).